MDM2 (MDM2 proto-oncogene)
Diseases named in the same sentence as MDM2 in open-access papers (continued):
Sharing a sentence is not in itself a finding about the gene and the disease.
breast carcinoma (continued). "MDM2 and MDM4 also enhance the tumorigenicity of breast cancer cells in in vitro and in vivo models and are overexpressed in primary human breast cancers." (PMID 26909605, 2016). "Our study proved that MDM2 has a critical role in inducing EMT, thus promoting breast cancer metastasis." (PMID 27184007, 2016). "Like MDM2, MDM4 also plays a protumorigenic role in human breast cancer cells that are cultured in vitro or in vivo as murine xenografts." (PMID 26909605, 2016). "Therefore, MDM2 may promote EMT of breast cancer via upregulating Snail." (PMID 27184007, 2016). "Both MDM2 and MDMX function as powerful oncogenes and are commonly over-expressed in some cancers, including sarcoma (~20%) and breast cancer (~15%)." (PMID 26858935, 2016). "Therefore, we hypothesized that MDM2 and EMT are associated in breast cancer." (PMID 27184007, 2016). "First, the inhibitory effects of JapA on the expression of NFAT1 and its target genes, MDM2, c-Myc and COX-2, were shown in human breast cancer cells in vitro and breast xenograft tumors in vivo." (PMID 26461225, 2015). "In terms of its breast cancer-promoting properties, Smad3/4 transcription factors activated by TGF-β1 bind to the promoter region of MDM2 to increase its protein expression." (PMID 25278993, 2014). "We found that MDM2 and SFRP1 transcripts were positively correlated with relapse free survival for all breast cancer subtypes and the results were statistically significant." (PMID 25278993, 2014). "Specifically, breast cancer cells overexpressed GINS2, TTK, CEP192, and shugoshin 1 and have lower levels of C-Nap1, semaphorin 6A, MDM2 and SFRP1." (PMID 25278993, 2014).
breast carcinoma (continued). "A human homologue of the murine double minute 2 (MDM2) gene (also known as HDM2 in humans) is frequently overexpressed in several types of human cancer, particularly in breast carcinomas and soft tissue sarcomas." (PMID 23624782, 2013). "Immunohistochemistry was performed using antibodies to PLK1, MDM2 and Ki67 on Tissue Micro-Array (TMA) slides of a cohort of 215 primary breast cancers." (PMID 22405092, 2012). "MDM2 is overexpressed in a variety of human cancers, including melanoma, non-small cell lung cancer (NSCLC), breast cancer, esophageal cancer, leukemia, non-Hodgkin's lymphoma and sarcoma." (PMID 21504625, 2011). "LncRNA NRON binds to murine double minute 2 (MDM2) and MDMX, respectively, and induces heterodimerization between them, thereby enhancing the E3 ligase activity of MDM2 toward tumor suppressor substrates and promoting tumorigenesis in breast cancer." (PMID 39937018, 2025). "Moreover, MDM2 has also been shown to down-regulate the abundance of MMP3, MMP10, and MMP13, with a role in inhibiting the invasion of breast cancer cells." (PMID 39759114, 2025). "In breast cancer models, CHD1L transcriptionally upregulates MDM2, as shown by cDNA microarray analysis and confirmed via Western blot, where CHD1L overexpression increased MDM2 protein levels, and CHD1L knockdown reduced them." (PMID 40442742, 2025). "MDM2 gene amplification or protein overexpression has been reported in a range of human malignancies, including dedifferentiated liposarcoma (DDLPS), breast cancer, glioblastoma, colorectal cancer, non-small-cell lung cancer (NSCLC), and urothelial carcinoma among others." (PMID 41515979, 2025). "In that capacity, mdm2 is a promising but not yet utilized molecular target for the treatment of breast cancer, however, its inhibition by small molecules is rather inappropriate." (PMID 40452017, 2025). "This suggests that MDM2 inhibitors may be a crucial strategy to overcome resistance to endocrine therapy and CDK4/6i in ER + breast cancer." (PMID 40949156, 2025). "MDM2 overexpression in the absence of MDM2 amplification has been reported in malignant melanoma, Burkitt lymphoma, carcinoma of the breast, carcinoma of the bladder, and soft tissue sarcomas." (PMID 38396916, 2024).
breast carcinoma (continued). "Notably, we discovered novel miRNAs that target MDM4 and MDM2; this study enhances our understanding of the YAP1/Hippo pathway and the functions of miRNAs as novel therapeutic targets in breast cancer." (PMID 39345743, 2024). "Breast cancer metastasis is promoted by multiple factors including notable contributors such as C-X-C chemokine receptor 4 (CXCR4 also known as CD184), Mouse Double Minute 2 (MDM2), and Mouse Double Minute 4 (MDM4 also known as MDMX)." (PMID 39766093, 2024). "To comprehensively examine whether FKBP52 affects MDM2 mRNA expression, we determined the correlation coefficient between FKBP52 protein and MDM2 mRNA expression using the breast cancer proteome database." (PMID 38803221, 2024). "However, since MTF2 regulates MDM2 expression and/or activity in AML and breast cancer, we integrated MDM2 transcript levels into our analysis." (PMID 37895228, 2023). "Although the direct evidence for the involvement of Mdm2 in Akt-mediated cancer development is still lacking, Mdm2 S166D/S186D, but not wild-type Mdm2, synergizes with Neu overexpression to promote breast cancer development." (PMID 36180910, 2022). "Following this, we analyzed the expression of the ligases observing that most of them were not highly present in these tumors with the exception of MDM2 in breast cancer, lung, prostate and gastric cancer." (PMID 35249548, 2022). "Here, in the present study, we identified the regulation of the FoxO signaling pathway via the modulation of four genes i.e. MDM2, STAT3, IGF1R, and GRM1 which could support the functioning of the PI3K-Akt and EGFR signal against breast cancer pathogenesis." (PMID 36686654, 2022). "Notwithstanding, they still concluded that MDM2 was an independent negative prognostic marker in breast cancer." (PMID 34695137, 2021).
breast carcinoma (continued). "It was demonstrated, using immunostaining, that MDM2 overexpression as well as its nuclear localization are negative prognostic markers in breast carcinomas." (PMID 34572735, 2021). "The evidence suggests that MDM2 and MDM4 may play significant roles in breast cancer formation, progression, prognosis, and protection from cancer." (PMID 33669778, 2021). "The information may improve the assessment of prognostic and/or predictive value of MDM2 and MDM4 genotypes in breast cancer patients." (PMID 33669778, 2021). "Thus, this study aimed to investigate the relationship between SNPs in MDM2 (rs2279744, rs937283, rs937282) and MDM4 (rs1380576, rs4245739) and I–II stage breast cancer." (PMID 33669778, 2021). "However, one phase I/II trial (NCT03566485) is exploring the use of idasanutlin, an MDM2 antagonist, in stage III and IV ER+/HER2− breast cancer patients to determine its utility and safety." (PMID 34830174, 2021). "We detected MDM2, MDMX and TAB1 expression in 70 breast cancer tissues with IHC staining." (PMID 31892970, 2020). "The MDM2/MDMX inhibitor and DOX may block the cell cycle of drug-resistant breast cancer cells at the G2/M arrest via the induction of p2142,43." (PMID 31892970, 2020). "Therefore, more studies are needed to understand the roles of MDM2 and MDMX in promoting breast cancer phenotypes in the context of different subtypes of breast cancer." (PMID 30642351, 2019). "We sought to stratify the biological functions of MDMX and MDM2 and their impacts on breast cancer development, comparing metastatic and nonmetastatic breast cancer subtypes." (PMID 30642351, 2019). "In addition to MITF, other amplified and overexpressed genes are HER2 in 15%–20% of invasive breast carcinomas, MYC in 15-20% of breast cancer and several hematological malignancies, EGFR in squamous cell carcinomas, MDM2 in several cancer type." (PMID 31217906, 2019). "In nonmetastatic ERα+ T47D breast cancer cells, we generated in vivo evidence that MDM2 promoted tumor growth in response to estrogen signaling without promoting tumor-invasive properties." (PMID 30642351, 2019). "Our observation that MDMX and MDM2 signaling pathways are different in TNBC and ERα+ breast cells has set the stage for suggesting the use of these biomarkers to more accurately define the nature of breast cancer subtypes." (PMID 30642351, 2019). "The use of another DNA-PK inhibitor (NU7441) in MCF7 breast cancer cells did not modulate the p21CIP1/WAF1 or MDM2 protein levels at 24 h after IR, which is consistent with the unchanged pattern for most of our genes." (PMID 31847107, 2019). "The promoter SNPs rs117039649 (SNP285G>C) and rs2279744 (SNP309T>G) in intron 1 of the MDM2 gene (hereafter referred to as SNP285 and SNP309, respectively) were genotyped in an Austrian hospital-based case-control study of 406 breast cancer patients and 254 control subjects." (PMID 30691044, 2019).
breast carcinoma (continued). "MDM2 has been reported to directly interact with NICD1, which leads to the ubiquitination and the transcriptional activation of Notch1 signaling pathway in breast cancer cells." (PMID 28871126, 2017). "Gossypol has anti-cancer effects by dual-targeting MDM2 and VEGF in human breast cancer." (PMID 28274247, 2017). "However, breast cancer cells treated with WIP1 inhibitor are more sensitive to DNA damage-inducing chemotherapy and to MDM2 antagonist nutlin-3." (PMID 26883108, 2016). "The results showed that MDM2 was highly expressed in two invasive breast cancer cells (MDA-MB-231 and MDA-MB-435) compared with the noninvasive breast cancer cell (MCF-7) and mammary epithelial cell (HBL-100)." (PMID 27184007, 2016). "In conclusion, our results showed that MDM2 overexpression induces EMT, which may contribute to breast cancer metastasis." (PMID 27184007, 2016). "Copy number aberrations (CNAs) in known breast cancer driver genes present in the PDTXs included gains/amplifications of MYC (78%), CCNE1 (34%), ZNF703 (25%), CCND1 (31%), MDM2 (25%), and ERBB2 (9%) and deletions of PTEN (41%), PPP2R2A (72%), CDKN2A (47%), and CDKN2B (47%)." (PMID 27641504, 2016). "Since ERα-positive primary invasive breast carcinomas have elevated expression of MDM4 and MDM2 genes, we hypothesized that ERα mediates the upregulation of MDM4 and MDM2 in human breast cancer." (PMID 26909605, 2016). "The tissue-specific effects observed are also in line with the previously observed effect of the MDM2 SNP285G > C; where the C-allele is proposed to reduce the risk for ovarian, endometrial, and breast cancer, but not cancer of the prostate, lung, or colon." (PMID 26867771, 2016). "By doing so, we confirmed the MDM4 SNP34091CC/MDM2 SNP309 GG genotype to associated with reduced risk of breast cancer (OR = 0.47; 95% CI = 0.24–0.92, when compared with the highest risk genotype (MDM4 SNP34091AA/MDM2 SNP309GG), data not shown)." (PMID 26471763, 2015). "Thus, we examined the effect of MDM2 on MMP9 expression in vitro and assessed the correlation between the two proteins using immunohistochemical analysis of human breast cancer tissue." (PMID 24236052, 2013). "Previous studies have shown that the expression of MMPs, including MMP9, can be upregulated by MDM2, although this has not been show in breast cancer to date." (PMID 24236052, 2013).